IL18 (interleukin 18)
Diseases named in the same sentence as IL18 in open-access papers (continued):
Sharing a sentence is not in itself a finding about the gene and the disease.
eczema (7 papers, 2006 to 2023). "Induction of the upregulated expression of IL-18, IL-18BP, and IL-18R on human mast cells by Der p1 and OVA suggests the possibility that allergens may cause or aggravate eczema through an IL-18-associated mechanism." (PMID 28839348, 2017). "Finally, this study suggests that conditions, such as eczema, related to interleukin 18 may be associated with greater resilience to COVID-19." (PMID 34911594, 2021). "The results showed that plasma free IL-18 and free IL-18BP levels in eczema patients were higher than those in healthy controls." (PMID 28839348, 2017). "Molar concentration ratios of IL-18BP/IL-18 were 17.3 (11.2–23.0) and 9.93 (6.9–33.7) in plasma of HC subjects and patient with eczema, respectively." (PMID 28839348, 2017). "IL-18 induced also an increase in IL-18BP+ mast cells, but a reduction of IL-18R+ mast cells in mouse eczema skin." (PMID 28839348, 2017). "The results showed that IL-18 reduced the number of IL-18R+ mast cells in the skin of healthy mice and in uninflamed skin area of eczema mice by approximately 45.6% and 44.1%, respectively." (PMID 28839348, 2017). "In conclusion, the correlation of IL-18 and IL-18BP in eczema plasma suggests an important balance between IL-18 and IL-18BP in eczema." (PMID 28839348, 2017). "It was observed that IL-18 and IL-18BP was correlated well with each other in the plasma of patients with eczema and HC subjects." (PMID 28839348, 2017). "We have demonstrated that levels of IL-18 and IL-18BP were elevated in the plasma of patients with eczema." (PMID 28839348, 2017). "To further evaluate the role of IL-18R in eczema, we examined the effect of IL-18 on IL-18R expression on mast cells of eczema mice." (PMID 28839348, 2017). "The aim of the current study is to investigate the correlation of IL-18 with IL-18BP in eczema, altered expression of IL-18, IL-18R, and IL-18BP in mast cells from eczema skin or cell line." (PMID 28839348, 2017). "In conclusion, correlation of IL-18 and IL-18BP in eczema plasma suggests an important balance between IL-18 and IL-18BP in eczema." (PMID 28839348, 2017). "The top 3 highest levels of total IL-18 in patients with eczema were 30.3, 35.8, and 40.0 pM, and the corresponding levels of total IL-18BP were 182.2, 185.5, and 199.6 pM, respectively." (PMID 28839348, 2017). "IL-18 at 10 ng/ml provoked 3.1 and 1.5-fold increase in skin mast cells of healthy mice and uninflamed area of eczema mice." (PMID 28839348, 2017). "We therefore investigated the expression of IL-18, IL-18BP, and IL-18R on mast cells by using flow cytometry analysis and mouse eczema model." (PMID 28839348, 2017). "IL-18 provocation increased percentage of IL-18BP+ mast cells in both inflamed and uninflamed skin areas of mouse eczema skin by 38.2% and 26.2% in comparison with that in healthy skin of mice." (PMID 28839348, 2017). "In addition, it was shown that plasma levels of free IL-18 and IL-18BP were significantly higher in eczema patients than in healthy controls and that the IL-18BP/IL-18 molar concentration ratio was reduced." (PMID 36742296, 2023). "Notably, the role of interleukin-18 in immune function is also substantiated by its role in several auto-immune diseases (inflammatory bowel disease and eczema/dermatitis)." (PMID 34911594, 2021). "Using ELISA kits, we observed that levels of total IL-18, total IL-18BP, calculated free IL-18, and calculated free IL-18BP in the plasma of patients with eczema were elevated in comparison with HC subjects." (PMID 28839348, 2017). "However, little is known of the expression of IL-18R in eczema and influence of IL-18 on IL-18R expression on mast cells." (PMID 28839348, 2017). "Nevertheless, the ability of IL-18 in provocation of increased IL-18BP+ mast cells in both inflamed and uninflamed areas of mouse eczema skin suggests that enhanced plasma level of IL-18BP in eczema may be partially released from mast cells induced by IL-18." (PMID 28839348, 2017).
eczema (continued). "Therefore, a molar concentration ratio of free plasma IL-18BP/IL-18 appears to be a key factor to determine the role of IL-18 in eczema." (PMID 28839348, 2017). "An imbalance between IL-18 and IL-18BP may account for increased IL-18 activity in eczema." (PMID 28839348, 2017). "Therefore, the anti-IL-18 therapy may be useful for the treatment of eczema." (PMID 28839348, 2017). "The decrease in molar concentration ratio of plasma IL-18BP/IL-18 and allergen-induced upregulated expression of IL-18 and IL-18R in skin mast cells of the patients with eczema suggests that anti-IL-18 including IL-18BP therapy may be useful for the treatment of eczema." (PMID 28839348, 2017). "Since the current experiment demonstrated that the molar concentration ratio of free plasma IL-18BP/IL-18 was 9.93 in the patient with eczema, it seems likely not enough IL-18BP to inhibit proinflammatory actions of IL-18 in eczema." (PMID 28839348, 2017). "Although it is not significant, eczema skin mast cells seem to produce less IL-18BP than HC skin mast cells, which supports the view that IL-18 play a role in eczema via reduced IL-18BP production in the body." (PMID 28839348, 2017). "However, the plasma/serum level of IL-18BP in eczema and correlation between IL-18 and IL-18BP have not been investigated." (PMID 28839348, 2017). "However, the expression levels of IL-18, its receptor IL-18R, and its antagonist IL-18BP in mast cells of eczema have not been investigated." (PMID 28839348, 2017).
encephalitis (7 papers, 2016 to 2025). An acute inflammatory process affecting the brain parenchyma. "In contrast, compared to HC, patients with encephalitis had elevated serum levels of IL-1b and CSF levels of G-CSF, IL-18 and MIG." (PMID 35479062, 2022). "IL-18 was detected within glial cells and neurons in the brain of subjects affected by tuberous sclerosis and encephalitis whereas in healthy subjects, only a weak IL-18 positivity was detected at the level of glial cells." (PMID 26728085, 2016). "IL-18 was localized by immunohistochemical analysis in brain sections obtained from tuberous sclerosis and encephalitis patients, as well as from gender- and age-matched controls, and in the brain sections of both Reeler and wild-type mice." (PMID 26728085, 2016). "Our results, showing higher number of IL-18-positive cells in the brain of viral encephalitis patients confirm these results." (PMID 26728085, 2016). "Furthermore, monocyte/macrophage production of IL-1β and IL-18 is critical to prevent severe HSV disease in encephalitis, keratitis, and vaginal infection in mouse models." (PMID 32101570, 2020). "CASP-1, IL-1β, and IL-18 were also expressed in the brain of mice with advanced rabies encephalitis (infected intramuscularly), at higher levels compared to the values that we obtained from the mice that had been infected intracranially and euthanized before advanced signs of encephalitis appeared." (PMID 29615985, 2018). "In order to check whether a similar difference was also present in the brain, we evaluated the expression of IL-18 by immunohistochemistry in the brain sections (Limbic regions/Frontotemporal cortex + tuber) obtained from patients with encephalitis, tuberous sclerosis, or controls." (PMID 26728085, 2016). "IL-18 was localized within reactive astrocytes in the hippocampus of patients with medically intractable temporal lobe epilepsy as well as in reactive astrocytes of patients with viral encephalitis and in reactive astrocytes and giant cells in cortical tubers of TSC patients." (PMID 26728085, 2016). "The release of IL-18 and IL-1β from monocytes/macrophages is critical for protection from HSV-1 based on animal models of encephalitis and genital infection, yet if and how HSV-1 activates inflammasomes in human macrophages is unknown." (PMID 32101570, 2020).
Fulminant hepatitis (7 papers, 2014 to 2025). Acute hepatitis complicated by acute liver failure with hepatic encephalopathy occurring less than 8 weeks after the onset of jaundice. "When host factors were studied, it was found that some subjects with fulminant hepatitis exhibit higher interleukin-18 (IL-18) levels in hepatocytes and macrophages, thus leading to an excessive NK cells response." (PMID 37243166, 2023). "NLRP3 is a component of the inflammasome pathway that regulates maturation of the inflammatory cytokines interleukin (IL)-1b and IL-18, and in the absence of REV-ERBα, dysregulated expression of Nlrp3 leads to increased IL-1b and IL-18 and susceptibility to fulminant hepatitis." (PMID 39872076, 2022). "Overall, IL-18-/- mice are still sensitive to MHV-3 infection, suggesting that IL-18 is not essential in MHV-3-mediated fulminant hepatitis." (PMID 26367131, 2015).
gastritis (7 papers, 2015 to 2025). Inflammation of the stomach. "IL-1β, IL-6, and IL-8 were lower in H. pylori infection-associated gastritis samples, whereas the levels of IL-12, IL-18, and TNF-α were higher." (PMID 38561502, 2024). "As observed in our study, the elevated levels of IL-18 in H. pylori-associated gastritis underscore its potential role in the severity and progression of gastritis, particularly in the context of H. pylori infection." (PMID 38561502, 2024). "A study in 2023 on peptic ulcer disease found that the expression of NLRC4, NLRP12, IL-18 and IL-1β decreased significantly in patients of peptic ulcer disease compared with those of only H. pylori-associated gastritis." (PMID 37833958, 2023). "In this study, we further addressed Rabeprazole inhibited cell pyroptosis by destroying NLRP3 inflammasome, leading to decrease Caspase-1 activation and IL-1β and IL-18 release, and resulting in alleviating H. pylori-associated gastritis." (PMID 34266494, 2021). "Our experimental study found that IL-18 levels were elevated in gastritis compared to normal, with even higher levels observed in H. pylori-associated gastritis than in H. pylori-independent gastritis." (PMID 38561502, 2024). "IL-1β, IL-18 have been shown to contribute to H. pylori induced gastritis, but the details of inflammation and association of virulence factors remain unclear." (PMID 27014647, 2015). "The correlation between expression levels of mature caspase-1 and mature IL-18 was significant in patients with gastritis infected with H. pylori." (PMID 40563885, 2025). "Conversely, IL-18 levels were reduced in infected gastritis cases, diverging from previous reports, although animal models suggest temporal variability in IL-18 responses, potentially explaining our results." (PMID 40563885, 2025). "Expression of the pro and mature forms of IL-18 is decreased with H. pylori infection, especially the amount of pro-IL-18, which is significantly higher in uninfected gastritis patients than in infected patients." (PMID 40563885, 2025). "Generally, cytokine levels were higher in gastritis, but in H. pylori-infected gastritis, IL-1β, IL-6, and IL-8 levels were lower compared to H. pylori-independent gastritis, while IL-12, IL-18, and TNF-α levels were higher." (PMID 38561502, 2024). "Key cytokines identified as playing a crucial role in the development and progression of gastritis include IL-1β, IL-6, IL-8, IL-12, IL-18, and TNF-α23–26." (PMID 38561502, 2024). "Our investigation delves into the differential expression of key cytokines in gastric tissue, including IL-1β, IL-6, IL-8, IL-12, IL-18, and TNF-α in the context of H. pylori-associated and H. pylori-independent gastritis." (PMID 38561502, 2024). "Similarly, while mature IL-18 was upregulated, infected gastritis patients in whom the pro form was downregulated (20% of the population) were more common than when the two forms were upregulated together." (PMID 40563885, 2025). "IL-18 expression is frequently altered simultaneously in infected gastritis patients (60%)." (PMID 40563885, 2025). "Our study provides invaluable insights into the inflammatory mechanisms involved by exploring key cytokines such as IL-1β, IL-6, IL-8, IL-12, IL-18, and TNF-α in gastritis." (PMID 38561502, 2024). "Commercially available ELISA plates were used to confirm further the influence of H. pylori infection on the expression of cytokines (IL-1β, IL-6, IL-8, IL-12, IL-18, and TNF-α) in gastritis." (PMID 38561502, 2024). "In H. pylori infection-associated gastritis, the IL-1β, IL-6, and IL-8 were lower, whereas IL-12, IL-18, and TNF-α were higher than those in gastritis without H. pylori infection." (PMID 38561502, 2024). "Focusing on Il-1β, IL-6, IL-8, IL-12, IL-18, and TNF-α, we analysed gene and protein levels to differentiate between H. pylori-infected and non-infected gastritis." (PMID 38561502, 2024).
gastritis (continued). "In contrast, the IL-12, IL-18, and TNF-α levels were higher in H. pylori-infected gastritis compared to non-infected gastritis." (PMID 38561502, 2024).
HCMV infection (7 papers, 2014 to 2024). "This study examines the impacts of 2 single-nucleotide polymorphisms (SNPs) in the promoter region of the IL-18 gene, -607C/A (rs1946518) and -137G/C (rs187238), on the incidence of delayed-onset CMV infection in patients undergoing kidney transplant." (PMID 31660404, 2019). "In contrast to NKG2C+ adaptive NK cells in HCMV infection, BP‐elicited memory‐like NK cells are highly sensitive to innate cytokines, such as IL‐12 and IL‐18, owing to upregulation of IL‐12/IL‐18 receptors and T‐bet." (PMID 38957437, 2024). "In this study, we observed that the IL-18 promotor SNP haplotype had a strong influence on the incidence of CMV infection and/or disease, but only among the patients who received prophylaxis." (PMID 31660404, 2019). "Previous reports have described that after HCMV infection or priming with IL-15+IL-12+IL-18, NK cells can display memory-like properties and the ability to stably produce high amounts of IFN-γ after rechallenge." (PMID 25329659, 2014). "The risk of CMV infection and/or disease was no different according to IL-18 haplotype in patients who did not receive prophylaxis." (PMID 31660404, 2019). "The findings suggest that IL-18 promotor SNPs could be useful predictive markers to optimize prophylaxis against CMV infection in kidney transplant recipients, although large, controlled, multicentric studies are needed to confirm them." (PMID 31660404, 2019). "In the univariate analysis, the factors associated with an increased risk of CMV infection were as follows: recipient age, cold ischemia time, delayed graft function, CMV prophylaxis, thymoglobulin, mTOR inhibitor, vascular rejection, and CG carriers of the IL-18 haplotype." (PMID 31660404, 2019). "(iii) Several researchers reported that HCMV infection induces the secretion of inflammatory cytokines such as interleukin (IL)-1β in serum of renal transplant recipients who developed a primary HCMV infection and IL-18 produced by HCMV-infected gingival fibroblasts." (PMID 28219398, 2017).
helminth infections (7 papers, 2014 to 2023). "IL-18-deficient mice show enhanced allergen-induced inflammation and exacerbation of chronic helminthic infections, suggesting the context-dependent role of IL-18 in type 2 immunity." (PMID 37910490, 2023). "From precedents in other helminth infections, IL-1β (and IL-18) could contribute to local inflammation, downregulate Th2 responses, and/or promote Th1 and Th17 responses, both of which are detectable in cystic echinococcosis (28, 58, –, 60)." (PMID 32571988, 2020). "Therefore, in a helminth infection in which a Th2 type immune response is important, IL-18 has a different role depending on the nematode type and may play an important role in host defense." (PMID 30717382, 2019). "Furthermore, because IL-18 activates Th2 cytokine production and granulocytes in the absence of IL-12, it also acts defensively in helminth infection." (PMID 30717382, 2019).
hypertriglyceridemia (7 papers, 2012 to 2024). A laboratory test result indicating elevated triglyceride concentration in the blood. "IL-18 (mRNA) in skeletal muscle appears to be involved in the regulation of intramuscular lipid metabolism and hypertriglyceridemia." (PMID 29342149, 2018). "IL-1 mediates fever, hyperferritimia, coagulopathy, and production of IL-18; IL-18 likely mediates hypersplenism, hypertriglyceridemia, hypotension, and elevated IFNγ." (PMID 30459597, 2018). "However, the previous study reveals that IL-18 knockout (IL-18 -/-) mice develop hypercholesterolemia, hyper-high-density-lipoprotein cholesterolemia, and hypertriglyceridemia while aging." (PMID 38774744, 2024). "Interestingly, the regression models show that cytokine (IL-18, IL-17) concentrations together with hypertriglyceridemia and tender joint counts in perPsA are connected." (PMID 35160217, 2022). "In conclusion, our findings suggest that muscular IL-18 may be involved in the regulation of intramuscular lipid metabolism and hypertriglyceridemia." (PMID 29342149, 2018). "Compared with IL18(+/+) mice producing IL-18, IL18 (−/−) mice developed hypercholesterolaemia, hyper-HDL cholesterolaemia, and hypertriglyceridaemia." (PMID 30413149, 2018). "In patients with MAS, free IL-18 significantly correlated with clinical status and biologic markers of MAS, such as anemia, hypertriglyceridemia, and hyperferritinemia, but also with markers of Th1 lymphocyte or macrophage activation, such as IFNγ and soluble receptors for IL-2 and TNFα." (PMID 30459597, 2018).
leishmaniasis (7 papers, 2016 to 2024). Infectious disease that is transmitted through the bite of hematophagous female phlebotomine sand flies. "The production of high levels of IL-18, along with high levels of IL-4 (Th2 biased response), has been associated with worse prognosis in other infections such as leishmaniasis." (PMID 33552997, 2020). "In this context, a weak association between the IL18 SNP rs1946519, and a higher risk to develop Leishmaniasis was described in Iranians." (PMID 27027876, 2016). "Interleukin (IL) IL-1β and IL-18 are important pro-inflammatory cytokines during innate immune responses to leishmaniasis, which are mediated by activation of NOD-like receptors (NLRs)." (PMID 38097942, 2023). "Meanwhile, treatment with IL-18 can serve to control leishmaniasis by inducing Th1 response and improve host resistant to reinfection by inducing and/or activating memory cells against Leishmania major infection." (PMID 30105037, 2018). "In contrast, during Leishmaniasis, Nlrp3 also promotes Th2-biased adaptive immunity in an inflammasome-dependent manner through IL-18." (PMID 27926940, 2016). "In another study aiming to understand the role of the NLRP3 inflammasome in Th1/Th2 responses during leishmaniasis, knockout BALB/c mice for NLRP3, ASC, or caspase-1, displayed deficient IL-1β and IL-18 production and were resistant to cutaneous L. major infection." (PMID 38623843, 2024). "However, it is necessary to fully elucidate the mechanisms behind the activation of the host’s immune responses in leishmaniasis, led by IL-18." (PMID 38097942, 2023). "However, over-expression of IL-18 exacerbates inflammation, suggesting a delicate pathophysiological role for IL-18, which has been documented in leishmaniasis." (PMID 33415318, 2020). "Recent advances in research have indicated crucial role for NLRP3 inflammasomes during Leishmaniasis.NLRP3 inflammasomes exert strong control over IL-1β and IL-18 production, and these cytokines are considered key mediators during Leishmania infections both in vitro and in vivo." (PMID 38623843, 2024).